PDCD1 (programmed cell death 1)
Diseases named in the same sentence as PDCD1 in open-access papers (continued):
Sharing a sentence is not in itself a finding about the gene and the disease.
non-small cell lung carcinoma (continued). "Although the blockade of programmed cell death 1 (PD-1)/PD-ligand (L) 1 has demonstrated promising and durable clinical responses for non-small-cell lung cancers (NSCLCs), NSCLC patients with epidermal growth factor receptor (EGFR) mutations responded poorly to PD-1/PD-L1 inhibitors." (PMID 30978241, 2019). "Immune checkpoint inhibitors (ICIs), most commonly programmed cell death-1 (PD-1) and programmed cell death-ligand 1 (PD-L1) inhibitors, have revolutionized the treatment and significantly improved the survival of patients with advanced non-small-cell lung cancer (NSCLC)." (PMID 38384808, 2024). "Recently, immune checkpoint inhibitors (ICIs), specifically programmed cell death-1/programmed cell death-ligand 1 (PD-1/PD-L1) antibodies, have demonstrated considerable potential in treating various types of cancer such as melanoma, non-small cell lung cancer, and renal cell cancer." (PMID 39218995, 2024). "Among an array of available ICI strategies, blockade of programmed cell death 1 (PD-1)/programmed cell death ligand 1 (PD-L1) axis has achieved the most promising results in a variety of malignant tumors, including melanoma, non-small cell lung cancer, renal cell carcinoma, and Hodgkin’s lymphoma." (PMID 36566230, 2022). "Over the last decade, immune checkpoint inhibitors, particularly inhibitors of the programmed cell death-1(PD-1)/programmed cell death ligand-1(PD-L1) axis, have transformed the therapeutic landscape in advanced non-small cell lung cancer (NSCLC) without driver mutations." (PMID 34526044, 2021). "In particular, monoclonal antibodies targeting programmed cell death 1 (PD-1) or its ligand (PD-L1) have been extensively studied in lung cancer, and their roles as first-line or second-line treatment in the management of advanced non-small cell lung cancer (NSCLC) patients are well established." (PMID 29137398, 2017). "Immune checkpoint mAbs such as anti-programmed cell death 1 (PD-1)/programmed cell death-ligand 1 (PD-L1) and CTLA-4 have shown durable responses in the treatment of melanoma, non-small cell lung cancer (NSCLC), and renal cancer carcinoma." (PMID 39171210, 2024). "Studies have shown that circ-HSP90A promotes cell growth and immune escape in non-small cell lung cancer by regulating STAT3 signal transduction and programmed cell death 1 (PD-1)/PD-L1 checkpoint." (PMID 36499715, 2022). "Antibody blockade of immune checkpoints Cytotoxic T Lymphocyte Antigen 4 (CTLA-4) and Programmed cell Death 1 (PD1)/PD1 ligand 1 (PD-L1) have been shown to restore antitumor immunity in multiple tumor types such as melanoma, renal cell carcinoma, non-small cell lung carcinoma and Hodgkin’s lymphoma." (PMID 35887186, 2022). "Nivolumab is an immune checkpoint inhibitor (ICI) that targets programmed cell death-1 (PD-1) receptors, and is used for the treatment of advanced non-small cell lung cancer (NSCLC) in patients who did not respond to first-line chemotherapy." (PMID 31842803, 2019). "Programmed cell death-1 (PD-1) and its ligand 1 (PD-L1) inhibitors have achieved good efficacy and safety in patients with advanced EGFR mutation-negative non-small cell lung cancer (NSCLC), but their efficacy in patients with previous EGFR mutations is limited." (PMID 37534246, 2023). "First-line cemiplimab (anti-programmed cell death-1 (PD-1)) monotherapy has previously shown significant improvement in overall survival (OS) and progression-free survival (PFS) versus chemotherapy in patients with advanced non-small cell lung cancer (aNSCLC) and PD-ligand 1 (PD-L1) expression ≥50%." (PMID 36008722, 2022).
lung cancer (196 papers, 2014 to 2026). A malignant neoplasm involving the lung. "The efficacy of anti‐CTLA‐4 antibody (ipilimumab) plus anti‐programmed cell death 1 antibody (nivolumab) in treating advanced non‐small cell lung cancer (NSCLC) is impeded by an elevated risk of severe immune‐related adverse events." (PMID 38828610, 2024). "The immune checkpoint inhibitors (ICIs), by targeting cytotoxic-T-lymphocyte-associated protein 4, programmed cell death 1 (PD-1), or PD-ligand 1, have dramatically changed the natural history of several cancers, including non–small cell lung cancer (NSCLC)." (PMID 35186013, 2021). "The evaluation of potential associations between the PDCD1 SNPs and lung cancer was performed only in few studies." (PMID 33519815, 2020). "Nowadays cancer immunotherapy, such as immune checkpoint inhibitors (ICBs) targeting cytotoxic T-lymphocyte associated antigen 4, programmed cell death 1 (PD-1), and programmed death ligand 1 (PD-L1), has revolutionized the treatments of a variety of different cancers, including lung cancer." (PMID 33213414, 2020). "ICIs such as CTL-associated protein 4 (CTLA-4), programmed cell death-1 (PD-1)/programmed death-ligand 1 (PD-L1), and their inhibitors, have been known as key factors for overcoming the immunosuppressive conditions in patients with malignancies including lung cancer." (PMID 35008367, 2021). "This study explores whether blood tumor mutational burden estimated by a next-generation sequencing gene panel is associated with clinical outcomes of patients with non–small cell lung cancer treated with anti–programmed cell death 1 and anti–programmed cell death ligand 1 agents." (PMID 30816954, 2019). "Immunotherapy, targeting the immune checkpoints Programmed cell death 1 (PD-1) and its ligand PD-L1, has been shown to prolong overall survival in patients with lung cancer." (PMID 40507880, 2025). "Immune checkpoint inhibitors (ICIs), including programmed cell death 1 (PD‐1) and programmed death‐ligand 1 (PD‐L1) inhibitors, have been used to treat various cancers, including non‐small cell lung cancer (NSCLC)." (PMID 40368363, 2025). "Tislelizumab, a programmed cell death-1 (PD-1) inhibitor, is approved in China for the treatment of classical Hodgkin lymphoma, lung cancer, hepatocellular carcinoma, and other malignancies." (PMID 41346629, 2025). "Immune checkpoint inhibitor (ICI) therapy, especially programmed cell death 1/ligand 1 (PD‐1/PD‐L1) therapy, has been recommended as a first‐line treatment for non‐small cell lung cancer (NSCLC)." (PMID 39592436, 2024). "As the crucial immune checkpoint, the programmed cell death-1 (PD-1)/PD-1 ligand 1 (PD-L1) axis contributes to lung cancer immunity." (PMID 37928424, 2023). "have revealed that SPP1+ macrophages and PDCD1+CXCL13+ activated T cells were correlated with the activation of lung cancer, indicating their essential role in cancer progression." (PMID 37846760, 2023). "In recent years, immune checkpoint inhibitors (ICIs), such as programmed cell death 1 (PD-1) and programmed cell death ligand 1 (PD-L1) inhibitors, have achieved remarkable efficacy in some lung cancer patients." (PMID 37035883, 2023). "Immune checkpoint inhibitors (ICIs) designed to block the programmed cell death-1 (PD-1) and programmed cell death-ligand 1 (PD-L1) pathways have revolutionized lung cancer treatment." (PMID 36555180, 2022). "The discovery of programmed cell death 1 (PD-1) and its ligand (PD-L1) improved the management of advanced-stage lung cancer by PD-1/PD-L1 blockade." (PMID 35528615, 2022). "More recently, immune checkpoint inhibitors (ICIs), particularly inhibitors of the programmed cell death 1 (PD-1) axis, have dramatically changed the landscape of lung cancer treatment." (PMID 36262349, 2022). "Clinical trials investigating TIGIT inhibitors alone or in combination with programmed cell death 1 (PD-1)/programmed cell death ligand 1 (PD-L1) inhibitors for lung cancer are currently underway." (PMID 36419396, 2022).
lung cancer (continued). "In particular, some programmed cell death 1 (PD‐1)/programmed cell death‐ligand 1 (PD‐L1) inhibitors have been clinically available for medical therapy of non‐small cell lung cancer (NSCLC) patients." (PMID 34907653, 2022). "Immune checkpoint inhibitors (ICIs), which evoke an antitumor T-cell response by targeting programmed cell death 1/programmed cell death ligand 1 (PD-1/PD-L1) or cytotoxic T-lymphocyte-associated antigen 4 (CTLA-4), have advanced the treatment of lung cancer." (PMID 35795657, 2022). "Immunotherapy with immune checkpoint inhibitors (ICIs) against programmed cell death 1 (PD-1/L1) axis has to be proven to aid the probabilities of long-term survival for advanced lung cancer patients." (PMID 33211206, 2021). "In recent years, inhibitors of the programmed cell death 1 (PD-1)/programmed death-ligand 1 (PD-L1) have shown strong anti-tumor activity and become standard anti-tumor treatments for patients with lung cancer." (PMID 33747922, 2021). "In the era of immuno‐oncology, inhibitors of programmed cell death 1 (PD‐1) and programmed cell death ligand 1 (PD‐L1) have provided robust survival benefits for patients with locally advanced and metastatic non‐small cell lung cancer (NSCLC)." (PMID 32134200, 2020). "Another target studied especially in melanoma, lung cancer, and Hodgkin lymphoma is programmed cell death 1 (PD-1)." (PMID 32508920, 2020). "T‐cell immunoglobulin and mucin‐domain containing 3 (TIM‐3), lymphocyte‐activation gene 3 (LAG‐3), and programmed cell death 1 (PD‐1) showed differential functional impact, tissue/cell distribution, and clinical significance in nonsmall cell lung cancer." (PMID 33135337, 2020). "The use of programmed cell death-1 (PD-1) pathway immune checkpoint inhibitors (ICIs) has become the standard of care for the initial treatment of advanced non–small cell lung cancer (NSCLC)." (PMID 32753547, 2020). "Immunotherapy with checkpoint inhibitor programmed cell death 1 (PD-1)/programmed death ligand-1 (PD-L1) antibodies demonstrates improvements in treatment of advanced non–small cell lung cancer." (PMID 30796165, 2019). "Recent advances in lung cancer treatment are emerging from new immunotherapies that target T-cell inhibitory receptors, such as programmed cell death-1 (PD-1)." (PMID 31333652, 2019). "Immune checkpoint blockade against programmed cell death 1 (PD-1) and its ligand PD-L1 often induces durable tumor responses in various cancers, including non–small cell lung cancer (NSCLC)." (PMID 30872362, 2019). "Blockade of programmed cell death ligand 1 (PD-L1)/programmed cell death 1 (PD-1) immune checkpoints by monoclonal antibodies has shown measurable success in cancer therapy against a variety of tumor types, including non–small-cell lung cancer (NSCLC)." (PMID 30126206, 2018). "al recently demonstrated improved efficacy of programmed cell-death 1 (PD-1) blockade in the presence of complement inhibition in reducing progression of tumors in a model of lung cancer." (PMID 30061895, 2018). "In the field of lung cancer, recent reports showed the certain clinical efficacy of lung cancer with programmed cell death-1 (PD-1) signal blockade with monoclonal anti-PD-1 antibody as well as ipilimumab." (PMID 27274999, 2016). "Immunotherapy has brought up new options for lung cancer patients, including blockade of immune checkpoints like cytotoxic T-lymphocyte-associated protein 4 (CTLA-4) and programmed cell death 1 (PD-1)." (PMID 27144518, 2016). "Pembrolizumab is an anti-programmed cell death-1 antibody (PD-1) currently under clinical evaluation primarily for metastatic cutaneous melanoma as well as lung cancer." (PMID 25516805, 2014). "Targeted therapies using immune checkpoint inhibitors (ICIs) to block the binding between programmed cell death-1 (PD-1) and programmed cell death ligand-1 (PD-L1) have achieved good responses in difficult-to-treat malignancies such as lung cancer and melanoma." (PMID 40416963, 2025).
lung cancer (continued). "Immune checkpoint inhibitors (ICIs) targeting programmed cell death 1 (PD-1), its ligand (PD-L1), and cytotoxic T-lymphocyte-associated protein 4 (CTLA-4) have emerged as a promising treatment option for lung cancer patients and can dramatically improve clinical outcomes." (PMID 38667328, 2024). "Moreover, abnormal expression of PDCD1 has been observed in several cancers, including esophageal cancer, breast cancer, lung cancer, and thyroid cancer." (PMID 39640266, 2024). "In addition, Pdcd1 expression showed strong positive correlation with Rab37 expression in lung cancer patients, while it was found to be weakly associated with Rab37 in normal tissues (n = 109)." (PMID 38321486, 2024). "For patients with advanced non–small cell lung cancer (aNSCLC) and obesity who potentially have an inadequate therapeutic response to anti–programmed cell death 1 therapy, is conventional chemotherapy or immune checkpoint inhibitor the optimal choice as first-line therapy?" (PMID 39093562, 2024). "For example, inhibition of apolipoprotein C1 (APOC1) restores ferroptosis sensitivity, leading to the conversion of tumor-associated macrophages from an M2 to an M1 phenotype and enhancing anti-PDCD1 immunotherapy against hepatocellular carcinoma and lung cancers." (PMID 38844964, 2024). "The 2016 Guideline for Treatment of Lung Cancer of The Japan Lung Cancer Society recommends testing patients with non-squamous NSCLC for multiple biomarkers, including EGFR gene mutation, ALK fusion, and programmed cell death 1 (PD-L1) expression." (PMID 37658334, 2023). "Lung cancer is an attractive context for current programmed cell death-1 (PD-1) and its ligand PD-L1 and Cytotoxic-T-lymphocyte-antigen-4 (CTLA-4) therapy due to its enhanced neo-antigen expression levels and ability to aid tumor cells in evading immune surveillance." (PMID 37182130, 2023). "In addition, the CXCL13+CD4+ T cell subset indicated in lung cancer has been described by high expression of exhaustion markers, including PDCD1, CTLA4, TIGIT, and HAVCR2, which is considered as an exhausted CD4+ T cell subpopulation." (PMID 37187731, 2023). "We retrospectively identified patients with advanced NSCLC who were treated with first- to third-line anti-programmed cell death-1 (PD-1) therapy from January 2016 through October 2017 at multiple institutions belonging to the Niigata Lung Cancer Treatment Group." (PMID 34631533, 2021). "Programmed cell death-1(PD-1)/programmed cell death-ligand 1 (PD-L1) inhibitors have shown a lasting anti-tumor response and can improve the survival rate in several malignant tumors including kidney cancer, bladder cancer, melanoma, and lung cancer." (PMID 34956906, 2021). "Since then, anti-programmed cell death 1 (anti-PD-1) antibodies, such as nivolumab and pembrolizumab, and anti-programmed death ligand 1 (PD-L1) antibodies, such as atezolizumab and durvalumab, have been developed and approved for lung cancer treatment." (PMID 32610470, 2020). "We aimed to compare intra- and extracranial responses to immune checkpoint inhibitors (ICIs) in lung cancer with brain metastases (BM), and to explore tumor microenvironments of the brain and lungs focusing on the programmed cell death-1 (PD-1)/programmed cell death ligand-1 (PD-L1) pathway." (PMID 30616523, 2019). "Programmed cell death ligand-1 (PD-L1) expression may predict the response to both programmed cell death-1 and PD-L1 inhibitors in lung cancer." (PMID 29049375, 2017). "On the other hand, immune-checkpoint inhibitors targeting programmed cell death-1 in lung cancer patients may not cause arthralgia and muscular pain." (PMID 37841432, 2023). "However, Trms subsets in lung cancer exhibit distinct expression patterns that can be divided into three CD8 clusters: GZMK+CD8+ (high-level PDCD1, low-level ITGAE), ZNF683+CD8+ (low-level PDCD1, high-level ITGAE), and LAYN+CD8+ (high-level PDCD1 and high-level ITGAE)." (PMID 37187731, 2023).
lung cancer (continued). "A significant increase in the expression profile of immunoglobulin genes in BALF was found between lung cancer and healthy controls in a recent transcriptomics study, which generated a 53-gene signature that showed a significant correlation with inhibitory checkpoint PDCD1." (PMID 36552956, 2022). "Combination of immunotherapy and traditional chemotherapy, such as triple therapy for lung cancer that includes carboplatin, pembrolizumab (a programmed cell death-1 [PD-1] inhibitor), and pemetrexed, poses important diagnostic challenges, as all 3 of these drugs may lead to AKI." (PMID 34939017, 2021). "Recent advances in cancer immunotherapy involve blockade of cytotoxic T lymphocyte antigen-4 and programmed cell death 1 in order to reverse T cell exhaustion and reinvigorate immunity, which has translated to dramatic clinical remission in many cases of metastatic melanoma and lung cancer." (PMID 29033936, 2017). "Prostate cancer, lung cancer, and ccRCC have all been studied using monoclonal antibodies that target different immune checkpoint inhibitors (such as CTLA4, PDCD1, and LAG3)." (PMID 39014265, 2024). "In mouse models of lung cancer, targeting CPT1A with etomoxir induces ferroptosis and synergizes with anti-PDCD1 immunotherapy to enhance anti-tumor immunity." (PMID 38844964, 2024). "Firstly, scRNA-seq study described a cellular module termed Lung Cancer Activation Module (LCAM), which was composed of PDCD1+CXCL13+ activated T cells, IgG+ plasma cells, and SPP1+ macrophages." (PMID 37187731, 2023). "We have studied other solid tumors such as lung cancer and prostate cancer treated with CAR-T in combination with PDCD1." (PMID 36979400, 2023). "Immunotherapy targeting programmed cell death 1 (PD1) or its ligand, PD1 ligand 1 (PD-L1), has transformed the paradigm of lung cancer treatment." (PMID 34484468, 2021). "Furthermore, the results showed that high PD-1 (PDCD1) mRNA level patients had poor prognosis in acute myeloid leukemia, cutaneous melanoma and renal carcinoma (all P<0.05), but had no impact on pancreatic carcinoma, hepatocellular carcinoma, lung cancer and breast invasive carcinoma (all P>0.05)." (PMID 34326692, 2021). "What is the performance of toripalimab, a programmed cell death 1 (PD-1) antibody, and JS311, a novel PD ligand 1 (PD-L1) immunohistochemistry assay, among patients with non–small cell lung cancer?" (PMID 33017026, 2020). "We also discussed the therapeutic potential of TAM targeting as adjuvant therapy in the current treatment of lung cancer, particularly highlighting the TAM-centered strategies for improving the efficacy of anti-programmed cell death-1/programmed cell death-ligand 1 (anti-PD-1/PD-L1) treatment." (PMID 38022518, 2023). "Moreover, increased CD274, PDCD1, and CTLA4 levels are strongly related to the overexpression of POSTN in lung cancer, especially LUSC." (PMID 35508298, 2022). "This study aimed to identify novel single nucleotide polymorphisms (SNPs) of programmed death-1 (encoded by PDCD1) and its ligands, programmed death ligand 1 (CD274) and 2 (PDCD1LG2), associated with lung cancer risk in never-smoking women." (PMID 34631591, 2021). "Immune checkpoint inhibitors (ICIs) targeting the programmed cell death 1 (PD‐1)/programmed death‐ligand 1 (PD‐L1) axis have transformed the clinical management of patients with metastatic non‐small cell lung cancer (NSCLC) whose tumors bear no druggable oncogenic alteration." (PMID 36852704, 2023). "Treatment options for lung cancers include surgery, chemotherapy, radiotherapy as well as monoclonal antibodies targeting epidermal growth factor receptor (EGFR), anaplastic lymphoma kinase (ALK), programmed cell death 1 (PD-1) and programmed cell death ligand 1 (PD-L1)." (PMID 34765548, 2021).